WDR5 (WD repeat domain 5)
Diseases named in the same sentence as WDR5 in open-access papers (continued):
Sharing a sentence is not in itself a finding about the gene and the disease.
Parkinson disease (1 paper, 2023). A progressive degenerative disorder of the central nervous system characterized by loss of dopamine producing neurons in the substantia nigra and the presence of Lewy bodies in the substantia nigra and locus coeruleus. "BANF1, PCGF5, WDR5, RYBP and BRD2 are related to the immune process of Parkinson’s disease and can predict the occurrence of Parkinson’s disease, which is expected to become a new target for the diagnosis and treatment of Parkinson’s disease." (PMID 36813848, 2023).
preeclampsia (1 paper, 2023). Preeclampsia is a hypertensive disorder of pregnancy that is characterized by new-onset hypertension with proteinuria presenting after 20 weeks of gestation, and depending on mild or severe forms may initially present with severe headache, visual disturbances, and hyperreflexia. "In our study, we found that WDR5 weakened the proliferation and invasion of trophoblasts and promoted the development of late-onset preeclampsia by activating NF-κB." (PMID 38055397, 2023). "Compared with the normal pregnancy group and the si-WDR5 group, the weights of the fetus and the placenta in the late-onset preeclampsia group decreased significantly (P < 0.05)." (PMID 38055397, 2023). "In this study, by utilization of clinical samples in more restricted standards, as well as in-vitro and in-vivo experiments, we investigated the role of WDR5 and NF-κB in late-onset preeclampsia comprehensively." (PMID 38055397, 2023). "For the first time, this study found that increased WDR5 in the placenta is involved in the development of late-onset preeclampsia." (PMID 38055397, 2023). "Results showed that the 24-hour urine protein level of the late-onset preeclampsia group was significantly higher than that of the normal group and si-WDR5 group (P < 0.001)." (PMID 38055397, 2023). "The relationship between WDR5 expression in placentas from preeclampsia patients and patients’ clinical characteristics." (PMID 38055397, 2023). "Results showed that the protein and mRNA levels of WDR5 were visibly increased in placentas of late-onset preeclampsia patients." (PMID 38055397, 2023). "WDR5 expression was detected in normal placentas and placentas from late-onset preeclampsia patients." (PMID 38055397, 2023). "WDR5 was highly expressed in the placentas of late-onset preeclampsia patients." (PMID 38055397, 2023). "Besides, we found that the expression level of WDR5 in placenta tissues is positively associated with the severity of preeclampsia, indicating that WDR5 may serve as a biomarker to monitor the progress of late-onset preeclampsia, and to predict the prognosis of this disease." (PMID 38055397, 2023). "Moreover, we proved that targeting WDR5 alleviated late-onset preeclampsia progression significantly in mice model, indicating that WDR5 has therapeutic potential in late-onset preeclampsia." (PMID 38055397, 2023). "In this study, for the first time, we prove that the increased WDR5 in the placentas results in the attenuated proliferation and invasion of trophoblasts, while targeting WDR5 may serve as an approach for the treatment of late-onset preeclampsia." (PMID 38055397, 2023). "As we expected, compared to normal placenta, trophoblasts from placenta of late-onset preeclampsia patients showed over-activated NF-κB, while the knockdown of WDR5 rescued phenomenon of over-activated NF-κB observed in trophoblasts from placenta of late-onset preeclampsia patients." (PMID 38055397, 2023). "Moreover, WDR5 expression level and nuclear NF-κB level were significantly higher in the late-onset preeclampsia group than that in the normal group and the si-WDR5 group (P < 0.001)." (PMID 38055397, 2023). "We then tested the therapeutic value of WDR5 in late-onset preeclampsia using the mouse model." (PMID 38055397, 2023). "Our finding provides new insights into the role of WDR5 in late-onset preeclampsia development." (PMID 38055397, 2023). "In-vivo studies suggested that targeting WDR5 combated late-onset preeclampsia development." (PMID 38055397, 2023). "Finally, we tested the role of WDR5 using the mice late-onset preeclampsia model." (PMID 38055397, 2023).
cancer (84 papers, 2013 to 2026). A tumor composed of atypical neoplastic, often pleomorphic cells that invade other tissues. "Given its multifaceted roles, particularly in cancer biology, where it is frequently overexpressed and linked to oncogenesis, WDR5 has emerged as an attractive drug target." (PMID 40302551, 2025). "Upregulation of WDR5 is observed in several cancer types, and loss of WDR5 or inhibition of WDR5 interactions at the WIN binding site are sufficient to cause tumor cell apoptosis." (PMID 39056772, 2024). "The chromatin-associated protein WD Repeat Domain 5 (WDR5) is a promising target for cancer drug discovery, with most efforts blocking an arginine-binding cavity on the protein called the ‘WIN’ site that tethers WDR5 to chromatin." (PMID 38682900, 2024). "Here, we create a genetically encoded label-free sensorto identify the interaction between a motif of the MYC transcriptionfactor, a primary cancer driver, and WDR5, a chromatin-associatedprotein hub." (PMID 39049818, 2024). "Disruption of this interaction significantly impedes cell proliferation and tumor growth, highlighting the potential of the WIN site inhibitors of WDR5 as a way of therapeutic intervention of the PTENα/β associated cancers." (PMID 38744853, 2024). "The chromatin-associated protein WDR5 has been widely studied due to its role in histone modification and its potential as a pharmacological target for the treatment of cancer." (PMID 39056772, 2024). "WDR5 has been linked to a range of cancer types and is currently considered a promising target for anti-cancer therapeutics." (PMID 38876301, 2024). "WDR5 is highly expressed in various cancer cells and is associated with clinicopathological parameters and poor prognoses." (PMID 36483601, 2022). "WDR5, an oncogene often found in cancers, is associated with the proliferation, cell cycle, and apoptosis of cancer cells 29-32." (PMID 36483601, 2022). "Remarkably, thesomatic cancer mutations of WDR5 preferentially distribute withinand around an essential cavity, which hosts the WDR5 interaction (Win)binding site." (PMID 35613319, 2022). "WDR5 was highly expressed in many cancers, and overexpression of WDR5 is associated with advanced tumor stage and poor patient survival rate." (PMID 35371306, 2022). "Many studies reported that Wdr5 is also associated with cell senescence markers such as p21 and p16 in cancer cells." (PMID 36358925, 2022). "Small molecule binders of the “WIN” site of WDR5 that cause displacement from chromatin have been additionally implicated to be of broader use in cancer treatment." (PMID 31768400, 2019). "Disrupting the PTENα/β-WDR5 interaction by point mutations of the key interacting residues attenuates these effects, which indicates that novel therapies for cancer treatment could be potentially developed by targeting the interaction between PTENα/β and WDR5." (PMID 38744853, 2024). "Hence, WDR5 demonstrates a stronger association with cancer, in contrast to the broader involvement of RBBP4/7 in various common complexes." (PMID 38028543, 2023). "Besides, USP44 and WDR5 are also associated with the metastasis of cancer, such as the migration and invasion capability of cancer cells and vasculogenic mimicry 12, 13, 27, 36-38." (PMID 36483601, 2022). "Interestingly, we found that WDR5 was aslo upregulated in UM-UC-3 and T24 spheres, suggesting that WDR5 might associate with cancer stem cells." (PMID 25656485, 2015). "The WD repeat-containing protein 5 (WDR5) is involved in the pathways of chromatin organization, which plays a role in carcinogenesis and cancer therapy response." (PMID 41580526, 2026). "The process depends on the interaction of HBx alpha‐helical domain with WDR5, which recruits WDR5 to gene promoters, activates gene expression, and drives malignant tumor progression." (PMID 40060195, 2025).
cancer (continued). "By elucidating the structural basis for Kif2A-induced WIN-S7 pocket formation, we lay the groundwork for further exploration of the role of WDR5 in mitosis and cancer biology." (PMID 40302551, 2025). "Collectively, our findings not only elucidate the structural basis of the WDR5-Kif2A interaction but also reveal its therapeutic potential for treating diseases driven by chromosomal instability, including cancer." (PMID 40302551, 2025). "Leveraging on cancer cell dependency dataset, pharmacological tools, and genomic profiling, we find WDR5, a factor critical for depositing histone H3 lysine 4 (H3K4) methylation, to be an unexplored vulnerability in SS." (PMID 40267190, 2025). "It is too early to tell if WDR5-directed PROTACs can live up to their promise, or which of the two main approaches, if any, will impact cancer treatment." (PMID 38202281, 2024). "From this perspective, WDR5 exhibits a pro-cancer effect by positively modulating the expression of immune checkpoints and immune-suppressive cytokines." (PMID 39201460, 2024). "WDR5 is also frequently overexpressed in cancer, where its overexpression correlates with aggressive disease and poor clinical outcomes." (PMID 38682900, 2024). "Selective activation of the WDR5-MHC I pathway and/or selective inhibition of the WDR5–immune checkpoint and WDR5–cytokine pathways should be considered in WDR5-based epigenetic cancer immunotherapy." (PMID 39201460, 2024). "Although PROTACs are a recent entry into the WDR5 inhibitor arena, their potential for catalytic and comprehensive WDR5 inhibition in cancer is immensely appealing." (PMID 38202281, 2024). "At first blush, it makes sense that if inhibiting the WIN site of WDR5 offers therapeutic benefit in some malignant settings, then clearing the entirety of WDR5 and its “oncogenic” functions from a cancer cell should amplify and extend those benefits." (PMID 38202281, 2024). "WDR5 inhibitors were originally conceived as epigenetic modulators, proposed to inhibit cancer cells by reversing oncogenic patterns of histone H3 lysine 4 methylation—a notion that persists to this day." (PMID 38202281, 2024). "It is also a high-value target for anti-cancer therapies, with small molecule WDR5 inhibitors and degraders undergoing extensive preclinical assessment." (PMID 38202281, 2024). "In broad terms, therefore, the genesis of WDR5 inhibition for cancer therapy—reduced to practice in 2014 —is the notion of selective inhibition of MLL1." (PMID 38202281, 2024). "WDR5-H3K4me3 has a wide variety of regulatory roles in the cancer-immunity cycle and has been recognized as a cellular multi-masker." (PMID 39201460, 2024). "From this perspective, WDR5 shows an anti-cancer effect through positively modulating MHC I expression." (PMID 39201460, 2024). "Overall, our studies emphasize the role of the PTENα/β-WDR5 interaction in promoting oncogenic processes and provide a structural basis for development potential therapeutic targets for cancer treatment." (PMID 38744853, 2024). "Much of the excitement in pharmacologically inhibiting WDR5 has been tied to the extraordinary potential of epigenetic modulation as a targeted and cutting-edge approach to cancer therapy." (PMID 38202281, 2024). "Taken together, our findings suggest that the interaction between the SSSRRSS motif of PTENα and WDR5 is indispensable for PTENα-mediated cancer cell proliferation and tumor growth." (PMID 38744853, 2024). "Here, we describe an integrated multi-omic approach to characterize the mechanism of action of WDR5 WINi in MLL-rearranged cancer cells." (PMID 38682900, 2024). "It is well reported that the WDR5-H3K4me3 epigenetic axis has various regulatory functions in the cancer-immunity cycle and is often dysregulated in the tumor microenvironment." (PMID 39201460, 2024).
cancer (continued). "There has been expanding interest in the idea of targeting WDR5 for cancer therapy, a growing list of potential cancer indications, and a profound evolution of chemical matter, with orally bioavailable picomolar inhibitors now in hand for preclinical vetting." (PMID 38202281, 2024). "Here, we evaluate the prevailing notion of WDR5 inhibitors as epigenetic modulators and present a unified model for their mechanism of action as a unique type of ribosome-directed anti-cancer therapy." (PMID 38202281, 2024). "SET1A catalyzes H3K4 methylation and WDR5, which is overexpressed in cancer cells, is indispensable for SET1 COMPASS HMT activity." (PMID 37821650, 2023). "This includes the assessment of ABCG2-TOX3-WDR5 in other cancers as well as in tissue resident somatic stem cells, and leveraging ongoing efforts on the development of WDR5 inhibitors." (PMID 37713380, 2023). "WDR5 plays an important role in the occurrence and development of cancer by affecting the myc pathway, inhibiting DNA damage, inducing the expression of cyclin, and regulating epithelial-mesenchymal transformation." (PMID 36770884, 2023). "Comparable results were obtained in SUM149 and DU-145 cells, indicating that NF-κB drives SET1A and WDR5 in different types of cancer cells." (PMID 37821650, 2023). "In concert with these results and the demonstration that silencing WDR5 decreases NOTCH1 expression, we found that, like MUC1-C, WDR5 is necessary for the self-renewal of cancer cells." (PMID 37821650, 2023). "Additional new options are on the way, as most recent in vitro data suggest synergistic action of WDR5 and HDM2 inhibitors in SMARCB1-deficient cancer cells." (PMID 35864317, 2022). "More recently, WDR5 was found to physically interact with the proto-oncogene and transcription factor MYC to guide its chromatin binding and transcriptional activation, suggesting that WDR5 is a tractable target for MYC-driven cancers." (PMID 36043466, 2022). "On the other hand, WDR5 was recently discovered to broadly regulate the expression of ribosomal protein (RP) genes across multiple cell lines and cancer types." (PMID 36043466, 2022). "In terms of applying WDR5 inhibitors as a cancer therapy, our work has three important ramifications." (PMID 35115608, 2022). "Overall, our results indicated that MS67 was better than WDR5 PPI inhibitors in inhibiting cancer cell growth in vitro." (PMID 34586829, 2021). "Some of these WDR5 PPI inhibitors have been shown to exert antiproliferative effects in cancer cells." (PMID 34586829, 2021). "These negative results were largely in agreement to the reported effect of WDR5 KD/KO in these cells and data in the Cancer Cell Line Encyclopedia database and suggested that MS67 is not a nonselective cytotoxic agent." (PMID 34586829, 2021). "In this study, we investigated pharmacological degradation of WDR5 as an alternative therapeutic strategy to pharmacological inhibition of WDR5 for the treatment of WDR5-dependent cancers." (PMID 34586829, 2021). "Although the core subunits of KMT2 complexes such as WDR5, RBBP5, DPY30, and ASH2L are rarely deleted or carry genetic mutations, they are frequently amplified or upregulated in human cancers and act as oncogenes." (PMID 33302406, 2020). "WDR5-MYC interaction also protects the cancer cells from replicative stress and DNA damage, as demonstrated in PDAC." (PMID 33302406, 2020). "Drugs targeting another WD repeat domain-containing protein—WDR5—are available and exhibited strong tumor suppression ability in several human cancers including hematologic malignancies." (PMID 32175272, 2020). "The previous studies have shown that WDR5 is a major driver of cell progression in various cancer types and its functional mechanism has been elucidated in CRC by triggering EMT process in response to the PI3K/AKT signaling pathway." (PMID 32478065, 2020).
cancer (continued). "The mechanism of action of WIN site inhibitors reveals new aspects of WDR5 function and forecasts broad therapeutic utility as anti-cancer agents." (PMID 31360909, 2019). "These compounds show cellular activity through displacement of WDR5 from chromatin, an effect that gives WDR5 inhibitors therapeutic relevance beyond MLL-r cancers." (PMID 31768400, 2019). "In general, the mechanism by which WDR5 supports cancer cells has been shown to be through increased target gene expression." (PMID 29925347, 2018). "Recent studies have revealed that WDR5 plays key roles in the tumorigenesis and progression of a variety of cancers." (PMID 30488017, 2018). "WDR5 has emerged as a prime target for anti-cancer drug discovery efforts, which have already been shown to selectively inhibit cancer cells carrying specific genetic lesions." (PMID 29385767, 2018). "In conjunction with the findings that WDR5 is overexpressed and required in cancer, WDR5 has been shown to physically interact with Myc and promote target recognition contributing to tumorigenesis." (PMID 29925347, 2018). "We also describe how its structure, conservation, and biological connections create opportunities for small molecule-mediated inhibition of WDR5, and how its multiple roles can influence the application of these inhibitors for anti-cancer therapeutics." (PMID 29385767, 2018). "Derivatives of the MLL/WDR5 interaction inhibitors with improved pharmacokinetic properties and in vivo bioavailability are expected to have the potential to be trialed in cancer patients." (PMID 30488017, 2018). "Promoters that become hypermethylated by depletion of EED or WDR5 were more than twice as likely to be represented among genes hypermethylated in cancer." (PMID 25071008, 2014). "We also provide evidence in support of the engagement of H3K4me2/me3 and WDR5/BPTF in H2A.Z-induced cancer pathogenesis." (PMID 24279307, 2013). "cMyc, another oncoprotein reported to be associated with WDR5 in cancer, was not substantially affected by the MS67 treatment in SS cells (see cMyc)." (PMID 40267190, 2025). "The success of this early campaign clearly demonstrated that WDR5 is a viable target for drug discovery, energizing both the quest for drug-like WDR5 inhibitors and the search for additional venues in which they can be used to ameliorate cancer." (PMID 38202281, 2024). "WDR5 and G9a were found to be essential in many types of cancers including NB." (PMID 38547242, 2024). "Previous studies have shown that WDR5 serves as an oncogene in a variety of cancers." (PMID 39350229, 2024). "In addition, WDR5 plays key roles in the progression of a variety of cancers, such as pancreatic cancer, breast cancer, and neuroblastoma." (PMID 39350229, 2024). "Indeed, tenuous assumptions about targeting WDR5 for cancer therapy are prevalent, and if unchallenged their impact is only likely to be amplified as these agents make their way to the clinic." (PMID 38202281, 2024). "WDR5 is considered a druggable cancer target and is being intensively investigated by others." (PMID 38821858, 2024). "But what unites most of them—apart from epigenetic roles—are two things: they were discovered in the last ten years and they receive little consideration in mainstream thinking about the mechanism of action and potential indications of WDR5 inhibitors as anti-cancer agents." (PMID 38202281, 2024).